TBX15 (T-box transcription factor 15)
Diseases named in the same sentence as TBX15 in open-access papers (continued):
Sharing a sentence is not in itself a finding about the gene and the disease.
cancer (continued). "However, TCGA pan cancer analysis of mRNA expression revealed that TBX15 expressions indicated a various trend according to the types of cancer." (PMID 33447348, 2020). "Next, we investigated the TBX15 mRNA expression in several cancers from TCGA." (PMID 33447348, 2020). "First we investigated whether the level of methylation at the CpG island located 3 kb upstream of the TBX15 TSS was related to TBX15 transcription in cancer cells." (PMID 27327083, 2016). "Also, those new findings might be one of clues for the discrepancy which several cancers indicated various TBX15 expressions." (PMID 33447348, 2020). "Furthermore, the link between TBX15 and NF-κB found in this study may be important to understand cancer and development processes." (PMID 27327083, 2016). "The expression of TBX15 in cancer is unknown, but because NF-κB modulated the expression of TBX15 we speculate that alterations of TBX15 expression would be expected in different types of cancer with consequences in cancer development." (PMID 27327083, 2016). "A panel of five DNA methylation markers (FER1L4, ZNF671, ST8SIA1, TBX15, and ARHGEF4) detected 74% of EC cancer patients with an overall specificity of 91%." (PMID 35242243, 2022). "Several have been proposed for the detection of PDAC or other cancers in blood, including BCAN, IKZF1, TBX15, BNC1 and SHOX2." (PMID 36434648, 2022). "Normal A and cancer 0 clusters shared expression of heat shock protein A (HSPA) and insulin growth factor–binding protein (IGFBP) genes, engagement of the heat shock factor 1 signaling pathway, and activity of SNAI1, RUNX3, and TBX15 transcription factors." (PMID 40215177, 2025). "While HepG2 cells are the other TBX15-expressing cancer cell line, they do not initiate transcription at the canonical 5′ end of TBX15 and, instead, use a liver promoter located in exon 6 of the main isoform (CAGE and GTEx data not shown)." (PMID 36547252, 2022). "In the ChIP-seq Unibind database, binding of various other transcription-stimulatory TFs was seen in the TSS-upstream and TSS-downstream Myob-hyperm DMRs in profiled human cancer cell lines, and endothelial cell cultures, and ESC (Unibind database), in which TBX15 is repressed." (PMID 36547252, 2022). "Many cancer cell lines that did not express TBX15 differed from normal cell strains in having high levels of DNA methylation throughout the region from TSS −20 to +9 kb, as seen in RRBS profiles." (PMID 36547252, 2022). "T-box transcription factor 15 (TBX15) is upregulated in a variety of tumors and has been reported to promote uncontrolled proliferation of tumor cells and induce tumor cells to avoid apoptosis, thus accelerating the malignant transformation of malignant tumors." (PMID 37328486, 2023). "However, other cancer cell lines without this promoter-overlapping DNA hypermethylation still did not express TBX15, like most non-transformed cell strains." (PMID 36547252, 2022).
tumor (10 papers, 2015 to 2025). "Higher expression levels of TBX15 and miR-152 were associated with decrease of tumor growth, lower expression of KIF2C, and more sensitivity to DOX treatment in both vivo and vitro." (PMID 34663310, 2021). "For this purpose, we further evaluated the clinical significance of TBX15 expression levels associated with tumor phenotype as well as with the prognosis of patients with HCC who underwent hepatectomy." (PMID 33447348, 2020). "The activity of TBX15 that may be associated with tumor progression and oncogenesis is unknown, and a few studies have addressed this question." (PMID 33447348, 2020). "Analysis of tumor tissues revealed that overexpression of TBX15 significantly decreased tumor growth." (PMID 34663310, 2021). "In our series, the levels of TBX15 mRNA in tumor tissues were significantly lower compared with those in nontumor tissues (p < 0.0001)." (PMID 33447348, 2020). "To further investigate the possible regulatory mechanism of TBX15 in tumor malignancy of HCC, we performed GSEA according to TBX15 expression." (PMID 33447348, 2020). "In contrast, a significant finding was that relatively low expression of TBX15 in tumor tissue was an independent prognostic factor for overall and disease-free survival." (PMID 33447348, 2020). "TBX15 mRNA levels in tumor tissues were significantly lower compared with those of nontumor tissues (p < 0.0001)." (PMID 33447348, 2020). "In respect to HCC, a study using optimized liquid hybridization capture-based bisulfite sequencing detected tumor-specific hypermethylation of the TBX15 promoter, suggesting its contribution to hepatocarcinogenesis." (PMID 33447348, 2020). "The present study presents an array analysis of DNA methylation that identified TBX15 as the most hypermethylated gene tumor tissue of patients with HCC." (PMID 33447348, 2020). "To explore the relationship between TBX15 methylation status and HCC tumor malignancy, we investigated the TBX15 methylation analysis of HCC patients from TCGA data." (PMID 33447348, 2020). "Among them, TBX15 of tumor tissue was the most hypermethylated (mean difference of beta-value = 0.518765)." (PMID 33447348, 2020). "Another validation set, which comprised 58 HCC with radical resection, was analyzed to investigate the relationships between tumor phenotype and TBX15 mRNA expression." (PMID 33447348, 2020). "We have previously discovered and/or characterized tumor-specific DNA methylation of six genes (APC, GSTP1, HOXD3, KLK10, TBX15, and TGFβ2) in radical prostatectomy tumor samples." (PMID 30470249, 2018). "In particular, the expression level of TBX15, which was negligible in most tumor types in the TCGA database, increased by approximately 100 times in this metastatic DFSP case." (PMID 28977029, 2017). "Other TFs, such as PITX3, RHOXF1, and TBX15, are involved in developmental and organogenesis pathways, suggesting a more plastic tumor phenotype that might support survival in diverse microenvironments." (PMID 41238550, 2025). "The link between TBX15 and immunosuppressive gene expression suggests that TBX15 may be involved in tumor immunology regulation." (PMID 37328486, 2023). "Different levels of TBX15 expression in distinct tumor types may imply their different biological functions and processes." (PMID 37328486, 2023). "In HCC with low TBX15 expression, ROS production could be moderate and contribute to the worse tumor malignancy." (PMID 33447348, 2020). "Therefore, we next allocated the patients according to the levels of TBX15 mRNA detected in tumor tissues (cutoff value = 0.5-fold) as follows: TBX15 high-expression group (n = 41) and TBX15 low-expression group (n = 17)." (PMID 33447348, 2020). "Therefore, genome-wide DNA methylation profiling indicates that hypermethylation and reduced expression of TBX15 in tumor tissue represents a potential biomarker for predicting poor survival of patients with HCC." (PMID 33447348, 2020).
tumor (continued). "In conclusion, reduced expression of TBX15 may serve as a potential biomarker for predicting tumor progression and poor survival as well as a target for antitumor therapy in HCC." (PMID 33447348, 2020). "In this study, we analyzed DNA methylation profiles in tumor tissue of HCC using those case series of our recent study, and found the most hypermethylated gene in tumor compared with nontumor tissues, encodes T-box 15 (TBX15), implicating TBX15 as a candidate regulator of tumor progression." (PMID 33447348, 2020). "In order to elucidate the effect of TBX15 on miR-152, KIF2C and PKM2 expression in vivo, we established tumor xenografts by implanting MCF7/ADR cells stably expressing TBX15." (PMID 34663310, 2021). "Among all genes in the focal amplifications, only five (TBX15, NOTCH2, PTGFRN, CNN3, and PHGDH) showed appreciably higher expression levels than those observed in tumor samples from the TCGA database." (PMID 28977029, 2017). "Using this approach, 7 genes were identified as undergoing tumor-specific aberrant promoter methylation in HCC, including IFITM1, SMAD6, TBX15, CHST4, and LRRC4 with hyper-methylated promoters and CCL20 and NQO1 with hypo-methylated promoters." (PMID 26300991, 2015). "These HLA-A24 ligands were possibly overexpressed in tumor samples and were therefore chosen as nonmutated TAA candidates of CRC111, which comprised peptides encoded by the KLK8, DEFA3, STRIP2, MMP1, FSCN1, TBX15, and PHLDA1 genes." (PMID 34185709, 2021). "We conducted a genome-wide analysis of DNA methylation of tumor and non-tumor tissue of 15 patients with HCC, and revealed TBX15 was the most hypermethylated gene of tumor (Beta-value in tumor tissue = 0.52 compared with non-tumor tissue)." (PMID 33447348, 2020). "And then, immunohistochemistry revealed that TBX15 protein expression in tumor tissue was weak compared to that of nontumor tissue." (PMID 33447348, 2020). "Further, TBX15 expression did not significantly correlate with tumor status, except for serum DCP levels." (PMID 33447348, 2020). "In our validation set comprising 58 patients with HCC, we found that TBX15 mRNA expression was significantly reduced in tumor tissues compared with that of nontumor tissues, likely because of TBX15 hypermethylation." (PMID 33447348, 2020). "In TCGA data, TBX15 mRNA expression was significantly lower in tumor tissue of HCC compared to nontumor tissue in HCC patients, as well." (PMID 33447348, 2020). "Third, we did not determine the actual mechanism of TBX15 for tumor malignancy in basic experiment." (PMID 33447348, 2020). "Similarly, genome-wide DNA methylation analysis revealed that the promoter region of TBX15 is hypermethylated and may therefore serve as marker to classify tumor and nontumor tissues." (PMID 33447348, 2020). "We found that 7 genes (IFITM1, SMAD6, TBX15, CHST4, LRRC4, CCL20, and NQO1) showed significantly different promoter methylation levels between tumor and non-tumor tissue (P value < 0.001) in approximately 80 % of the 78 HCCs." (PMID 26300991, 2015). "However, TBX15, LRRC4, and CHST4 showed no systematic difference in expression between HCC and non-tumor liver cell lines." (PMID 26300991, 2015).
metabolic disease (3 papers, 2015 to 2020). A congenital disorder (due to inherited enzyme abnormality) or acquired (due to failure of a metabolically important organ) disorder resulting from an abnormal metabolic process. "These metabolic disorders were hypothesized to be induced by elevated levels of mRNA expression of T-box 15 (Tbx15) and glypican 4 (Gpc4) in subcutaneous and visceral adipose tissues respectively." (PMID 32435260, 2020).
TBX15 also shares sentences with these, for which no sentence is quoted: osteoporosis (2 papers); astrocytoma (1); benign tumors (1); Brachycephaly (1); cholangiocarcinoma (1); cleidocranial dysplasia (1); congenital heart malformation (1); dwarfism (1); dysplasia (1); endometriosis (1); Endove syndrome (1); gastric cancer (1); hematological neoplasms (1); human papillomavirus infection (1); Insulin resistance (1); liver cancer (1); metabolic syndrome (1); Mowat-Wilson syndrome (1); pancreatic cancer (1); placental diseases (1); rhabdomyosarcoma (1); Sagittal craniosynostosis (1); sarcoma (1); systemic sclerosis (1); tumor of the thyroid (1).